PCDH10 (protocadherin 10)
Diseases named in the same sentence as PCDH10 in open-access papers (continued):
Sharing a sentence is not in itself a finding about the gene and the disease.
multiple myeloma (6 papers, 2012 to 2024). "In multiple myeloma cells, rescue of Pcdh10 expression induces apoptosis by impeding the the NF-κB pathway, and suppresses cell proliferation via the negative modulation of Wnt/β-catenin/BCL-9 signaling." (PMID 37058252, 2023). "Induction of apoptosis by re-expression of PCDH10 has been ascribed to inhibition of NFκB signalling in multiple myeloma, and to inhibition of the PI3K/AKT pathway in hepatocellular carcinoma cells." (PMID 35468745, 2022). "In multiple myeloma cells, re-expression of PCDH10 suppressed nuclear localization of β-catenin, activity of LEF/TCF, expression of the β-catenin transcriptional cofactor BCL9, and of AKT, whereas expression of GSK3β was increased." (PMID 35468745, 2022). "The tumorigenesis mechanisms of PCDH10 were most studied in the multiple myeloma(MM), while little is known in DLBCL." (PMID 29202805, 2017). "PCDH10 is broadly expressed in normal adult, but nearly undetectable in multiple myeloma (MM) tissues and cell lines." (PMID 22245948, 2012). "PCDH10 also appears to induce myeloma cell apoptosis by inhibiting the NF-kappaB pathway." (PMID 26276761, 2015).
non-small cell lung carcinoma (5 papers, 2015 to 2023). A group of at least three distinct histological types of lung cancer, including non-small cell squamous cell carcinoma, adenocarcinoma, and large cell carcinoma. "Patients with curatively resected pathological stage I non-small-cell lung cancer patients showed significantly worse survival (recurrence-free, overall or disease-specific) in case of PCDH10 promoter methylation." (PMID 35468745, 2022). "PCDH10 promoter methylation plays a significant role in the progression of non-small cell lung cancer and may be a promising prognostic marker for patients with curatively resected pathological stage I." (PMID 33369468, 2020).
autism spectrum disorder (4 papers, 2014 to 2025). A spectrum of developmental disorders that includes autism, and Asperger syndrome. "A protein called protocadherin 10 (Pcdh10), which is linked to autism spectrum disorder, interacts with polyubiquitinated PSD-95 and facilitates its delivery to the proteasome for degradation." (PMID 39940735, 2025). "Whereas prior to this study there has been no experimental literature implicating the role of Pcdh10 in drug abuse, the involvement of this gene in a neurodevelopmental disorder, autism spectrum disorder, has already been reported." (PMID 24884696, 2014). "Indeed, PCDH10 is an autism spectrum disorder gene, and a region (PIR, proteasome interacting region), shared by the C-termini of both short and long isoforms of Pcdh10, is instrumental in excitatory synapse elimination by linking ubiquinated PSD-95 to the proteasome." (PMID 35468745, 2022).
medulloblastoma (4 papers, 2021 to 2023). A malignant, invasive embryonal neoplasm arising from the cerebellum. "The aggravating effect of Pcdh10 ablation in this model confirms a tumor promoting role for Pcdh10 inactivation, fully in line with the frequent observations of PCDH10 silencing in human cancers, including medulloblastoma." (PMID 35468745, 2022). "However, Pcdh10 signaling has the opposite effect in medulloblastoma cells, where Pcdh10 expression is decreased due to DNA hypermethylation and histone modification, but its restoration impedes migration." (PMID 37058252, 2023). "As PCDH10 expression is frequently repressed in human medulloblastoma, which is originating in the external granular layer of the developing cerebellum, we checked the effect of Pcdh10 ablation in an established mouse model for medulloblastoma." (PMID 35468745, 2022).
schizophrenia (4 papers, 2011 to 2023). A major psychotic disorder characterized by abnormalities in the perception or expression of reality. "A large-scale single nucleotide polymorphism genotyping data on chromosome 4 suggested that Pcdh10 is one of the susceptibility genes of schizophrenia and bipolar disorder." (PMID 37058252, 2023). "In addition to ASD, several recent studies have implicated human Pcdh10 in other neurological conditions, such as familial amyloidotic polyneuropathy (FAP), obsessive–compulsive disorder (OCD), major depression (MD) and schizophrenia." (PMID 37058252, 2023). "Schizophrenia genes relevant to cell adhesion comprised of several members of the cadherin family CDH22, CDH4, CDH7 and CDH9 as well as the protocadherin PCDH10." (PMID 34859219, 2021).
diffuse large B-cell lymphoma (3 papers, 2017 to 2023). "Recently, promoter methylation of PCDH10 was found in diffuse large B-cell lymphoma (DLBCL) but not in normal lymph nodes, suggesting that its epigenetic aberrance is essential to the lymphomagenesis." (PMID 29202805, 2017).
endometrial cancer (3 papers, 2020 to 2023). Primary or metastatic malignant neoplasm involving the endometrium (mucous membrane that lines the endometrial cavity). "However, PCDH10 promoter hypermethylation is a frequent hallmark observed during the progression of cervical and endometrial cancers, as previously reported." (PMID 37058252, 2023). "According to GEO2R analysis, Pcdh10 is downregulated and is likely to be one of the most significant genes in tumor differentiation in endometrial cancer." (PMID 37058252, 2023). "In endometroid endometrial cancer cells with re-expressed PCDH10, transcription of the Wnt target gene MALAT1 was suppressed." (PMID 35468745, 2022). "Another research concerning endometrial cancer found that DEPDC1 is involved in cell proliferation and restrain apoptosis of endometrial cancer cell lines, and it promotes tumor growth through the PCDH10‐DEPDC1‐Caspase signal regulation pathway." (PMID 33140894, 2020).
hepatocellular carcinoma (3 papers, 2020 to 2023). A malignant tumor that arises from hepatocytes. "Low expression of PCDH10 mRNA in hepatocellular carcinoma specimens was associated with a worse overall survival and this was an independent prognostic indicator." (PMID 35468745, 2022). "In support of a role for Pcdh10 as a tumor suppressor, restoration of Pcdh10 in hepatocellular carcinoma cell lines inhibits proliferation and induces cell apoptosis via suppressing PI3K/Akt signaling pathway." (PMID 37058252, 2023). "PCDH10 is a tumor suppressor gene that reduces cell proliferation in hepatocellular carcinoma (HCC), and can induce cancer cell apoptosis via several routes." (PMID 32694982, 2020).
lung carcinoma (3 papers, 2015 to 2022). "This was corroborated by the identification of methylation-regulated genes (PCDH10, TBX2, and CDO1) recently described as biomarkers in localized lung cancers and premalignant lesions." (PMID 36461127, 2022). "Interestingly, PCDH10, TBX2, and CDO1 were described as potential biomarkers for early-stage lung cancers." (PMID 36461127, 2022).
lymphoma (3 papers, 2021 to 2023). A malignant (clonal) proliferation of B- lymphocytes or T- lymphocytes which involves the lymph nodes, bone marrow and/or extranodal sites. "In lymphomas, an inverse relationship between protein levels of PCDH10 and β-catenin was seen, but mRNA levels of β-catenin were not influenced by PCDH10 re-expression." (PMID 35468745, 2022). "Meanwhile, Pcdh10 could be a potential target gene for establishing epigenetic therapies in lymphomas." (PMID 37058252, 2023). "It is interesting to note that the methylation status of Pcdh10 may be able to predict the response of lymphomas to doxorubicin, a common chemotherapeutic drug used to treat a variety of human cancers." (PMID 37058252, 2023). "Moreover, silencing of PCDH10 contributes to chemotherapy resistance of leukemia and lymphomas and might therefore serve as an indicator of drug resistance." (PMID 35468745, 2022).
pancreatic ductal adenocarcinoma (3 papers, 2019 to 2023). An infiltrating adenocarcinoma that arises from the epithelial cells of the pancreas. "Recently, high methylation levels of Pcdh10 were found to correlate with worse progression-free survival rates instead of the overall survival, suggesting that Pcdh10 methylation status predicts poor prognosis in patients with pancreatic ductal adenocarcinomas." (PMID 37058252, 2023).
prostate carcinoma (3 papers, 2022 to 2024). A carcinoma that arises from epithelial cells of the prostate gland. "Increased PCDH10 promoter methylation was also significantly associated with increased malignancy (invasion, metastasis, recurrence) of prostate cancers, and an independent prognostic biomarker of worse recurrence-free survival of patients after radical prostatectomy." (PMID 35468745, 2022).
astrocytoma (2 papers, 2022 to 2023). "In human astrocytoma cell (U251), the cytoplasmic domain of Pcdh10 can interact with Nap1 and recruit the WAVE complex, and this interaction promotes adhesion and motility at the cell junctions to facilitate migration." (PMID 37058252, 2023). "Overexpression of Pcdh10 recruits the WAVE regulatory complex at inter-axonal contact sites, which results in reorganization of F-actin and N-cadherin at these locations, and subsequently regulates cell migration of astrocytoma U251 cells." (PMID 37058252, 2023). "The PCDH10-WRC interaction was shown to promote a kind of uncoordinated migration of astrocytoma cells in contact with each other, but not in case of solitary cells, probably by focal redistribution of N-cadherin." (PMID 35468745, 2022).
lymph node metastasis (2 papers, 2020 to 2023). "Since elevated PCDH10 levels correlated with lymph node metastasis, we speculated that PCDH10 may be involved in GC cell metastasis." (PMID 37147733, 2023). "PCDH10 methylation was more in tumor tissue and was associated with higher preoperative PSA level, higher Gleason Score, advanced clinical stage, lymph node metastasis, angiolymphatic invasion, biochemical recurrence and may be used as an independent predictor of BCR-free survival." (PMID 33369468, 2020).
Anxiety (1 paper, 2024). Intense feelings of nervousness, tension, or panic often arise in response to interpersonal stresses. "We used a combination of interneuron-specific conditional and ubiquitous Pcdh10 KO mice to zoom-in on certain neuronal cell populations, anxiety and socio-affective communication." (PMID 38889770, 2024). "Previous studies indicated that mice haploinsufficient for Pcdh10 displayed alterations in socio-affective communication through isolation-induced USV, a change typically associated with increased anxiety in the pup." (PMID 38889770, 2024). "This study highlights the involvement of Pcdh10 in anxiety-related behaviour and socio-affective communication in developing mice pups and implicates interneuron subpopulations in the behavioural alterations relevant to ASD." (PMID 38889770, 2024). "A KO model and the Gsh2:cKO model were therefore compared to investigate whether altered Pcdh10 expression in interneurons affects ultrasonic calling, as a measurement for anxiety." (PMID 38889770, 2024).
Castleman disease (1 paper, 2017). Castleman disease (CD) is a benign lymphoproliferative disorder that may present as a localized or multicentric form. "Our study also examined the RL/FH, chronic tonsillitis and Castleman diseases, and found that the frequency of PCDH10 methylation were 12.5%, 0% and 11.1% respectively." (PMID 29202805, 2017). "Among the 9 cases of Castleman diseases, only 1 was found PCDH10 methylation, and no methylation was detected in the 6 cases of chronic tonsillitis." (PMID 29202805, 2017).
cerebellar tumors (1 paper, 2022).
diabetes (1 paper, 2015). "PCDH10 on chromosome 4q, and unknown genes on chromosome 5q and chromosome 14q were significantly associated with lower risk of the YZ constitution after controlling for age, sex, diabetes duration, and hemoglobin A1c." (PMID 26169365, 2015).
encephalitis (1 paper, 2025). An acute inflammatory process affecting the brain parenchyma. "Imperial 181 does not bind VLDLR, ApoER2, or PCDH10, and has been shown to replicate poorly in the brain of infected mice, suggesting an impaired ability to infect neurons and cause encephalitis compared to virulent WEEV strains." (PMID 40187345, 2025).
endometriosis (1 paper, 2023). The growth of functional endometrial tissue in anatomic sites outside the uterine body. "Silencing EZH2 by siRNA reduced H3K27me3 enrichment and increased PCDH10 expression, resulting in decreased invasion and migration of endometrial stromal cells and providing a target for the treatment of endometriosis patients." (PMID 37058252, 2023). "Moreover, a recent study has reported that low expression of Pcdh10 is associated with high Enhancer of Zeste Homolog 2 (EZH2) expression and Histone H3 (H3K27me3) enrichment in the tissue of endometriosis patients." (PMID 37058252, 2023).
epilepsy (1 paper, 2020). A brain disorder characterized by episodes of abnormally increased neuronal discharge resulting in transient episodes of sensory or motor neurological dysfunction, or psychic dysfunction. "In particular, genes such as ANXA1, CNTN6, HLA-B, PCDH19, and PCDH10, have been linked to ASD, epilepsy, ID, and other neuropsychiatric disorders, were significantly upregulated or downregulated and warrant further investigation." (PMID 31921404, 2020). "The protocadherin genes, PCDH10 and PCDH19 that are linked to ASD and epilepsy were downregulated along with several members of Zinc-finger gene family of transcription factors." (PMID 31921404, 2020).
glioblastoma (1 paper, 2023). The most malignant astrocytic tumor (WHO grade IV). "In contrast, Pcdh10 has also been shown to be an oncogene for the tumorigenesis of glioblastoma." (PMID 37058252, 2023). "It should be noted that Pcdh10 might act as a tumor oncogene in gliomas, as it is essential for the proliferation and tumorigenicity of human glioblastoma cell lines GB2 and GB16." (PMID 37058252, 2023).
glioma (1 paper, 2023). A benign or malignant brain and spinal cord tumor that arises from glial cells (astrocytes, oligodendrocytes, ependymal cells). "Similarly, after treatment with cytochalasin H in U87MG malignant human glioma cells, the proliferation is inhibited along with upregulated Pcdh10 expression." (PMID 37058252, 2023).
head and neck cancer (1 paper, 2017). A primary or metastatic malignant neoplasm affecting the head and neck. "The PCDH10 and PCDH17 promoter regions are reported to be hypermethylated in uterine cervical cancer, head and neck cancer, and some gastrointestinal cancers." (PMID 29075151, 2017).
liver cancer (1 paper, 2022). An epithelial or non-epithelial malignant neoplasm that arises from the liver. "Several studies have shown that PCDH genes are also involved in liver cancer development, including PCDH10, PCDH17, PCDH19, PCDH20, PCDHGC4, and PCDHGC5." (PMID 36230503, 2022).
lung adenocarcinoma (1 paper, 2022). A carcinoma that arises from the lung and is characterized by the presence of malignant glandular epithelial cells. "The resulting 245 differentially methylated regions were enriched for lung adenocarcinoma-specific 5-mC patterns in TCGA data and indicated transcriptional repression of several genes described to be silenced in NSCLC (e.g., PCDH10, TBX2, CDO1, and HOXA9)." (PMID 36461127, 2022).
major depression (1 paper, 2023). "Similarly, 428 methylated genes, including Pcdh10, have been linked to early-onset major depression in an epigenome-wide association study of 75 monozygotic twin pairs." (PMID 37058252, 2023).
pancreatic adenocarcinoma (1 paper, 2019). "An exploratory study of methylation analysis on PCDHAC2, PCDHGC5 and PCDH10 was carried out in 11 pancreatic adenocarcinomas." (PMID 31088413, 2019). "Therefore, we extended BGS analysis of PCDH10 to the whole series of 23 pancreatic adenocarcinomas available." (PMID 31088413, 2019).
tobacco-use disorder (1 paper, 2017). "Gene-disease association shows SORCS1, SKAP2, and CELSR2 genes are related with genetic susceptibility, and genes SORCS1 and PCDH10 are related with tobacco-use disorder." (PMID 28079101, 2017).
Uterine leiomyoma (1 paper, 2017). The presence of a leiomyoma of the uterus. "Using total RNA prepared from our second panel of 26 matched specimens, we confirmed that ESR1, SOX18, CCL5, and PCDH10 but not CALCRL are differentially expressed in uterine leiomyomas or that levels of their expression vary by menstrual phase." (PMID 28637297, 2017).